FOXM1 (forkhead box M1)
Diseases named in the same sentence as FOXM1 in open-access papers (continued):
Sharing a sentence is not in itself a finding about the gene and the disease.
cervical carcinoma (65 papers, 2011 to 2025). A carcinoma arising from either the exocervical squamous epithelium or the endocervical glandular epithelium. "For example, ubiquitin-specific peptidase 21 can activate YAP via controlling FOXM1 stability, blocking Hippo signaling, lowering cell proliferation, causing apoptosis, and eventually increasing the radiosensitivity of cervical cancer cells." (PMID 39187525, 2024). "Interleukin-27 upregulates miR-6852-5p and causes necrosis in cervical cancer cells by inhibiting Forkhead box protein M1 (FOXM1) expression, with the FOXM1 being suppressed by FOXO3a." (PMID 36835100, 2023). "Over-expression of FOXM1 transcription factor network is linked to the development and pathogenesis of cervical cancer." (PMID 31888692, 2019). "FoxM1, a transcriptional factor and 14-3-3ζ downstream target, is associated with cervical cancer progression and pathogenesis." (PMID 29371981, 2017). "Our previous study showed FOXM1 expression was significantly up-regulated in cervical cancer, and was associated with poor prognosis." (PMID 28978307, 2017). "The viral oncoprotein E7, which belongs to the human papillomavirus responsible for causing cervical cancer as well as genital cancers such as vulvar, vaginal, anal and penile cancers, interferes with FOXM1 sumoylation, protecting FOXM1 from degradation, which increases cell proliferation." (PMID 35887358, 2022). "The aim of the present study was to investigate the effect of forkhead box M1 (FOXM1) to paclitaxel resistance in cervical cancer cells, to determine the underlying mechanism, and to identify novel targets for the treatment of paclitaxel-resistant cervical cancer." (PMID 35141332, 2022). "We have proved that FOXM1 level is associated with poor prognosis in early-stage cervical cancer patients in our previous studies, so we deduced that miR-216b may also be related to prognosis of cervical cancer patients." (PMID 28978307, 2017). "FOXM1, a key transcription factor in this cell subpopulation, significantly inhibited the proliferation and invasion of cervical cancer cells." (PMID 40589640, 2025). "CCK-8 showed that after FOXM1 knockdown, the cell viability of cervical cancer cells decreased significantly, and cell proliferation slowed down." (PMID 40589640, 2025). "This binding leads to the formation of a circARHGAP12/IGF2BP2/FOXM1 triplex complex, enhancing FOXM1 mRNA stability and promoting cervical cancer cell proliferation and metastasis." (PMID 39075555, 2024). "Another study shows that m6A-modified circ-231 interacts with IGFBP2 and binds to FOXM1 mRNA and further maintains the stability of FOXM1 mRNA, facilitating progression of cervical cancer." (PMID 38577609, 2024). "For instance, the activation of AMPK inhibited cervical cancer cell proliferation through AKT/FOXO3a/FOXM1 signaling cascade by counteracting the function of Forkhead box M1 (FOXM1)." (PMID 38255314, 2024). "For example, circARHGAP12 interacts with IGF2BP2 and contributes the stability of FOXM1 mRNA in cervical cancer." (PMID 35773744, 2022). "The association between FOXM1, ATP-binding cassette subfamily C member 5 (ABCC5), and cervical cancer cell drug resistance was assessed by overexpressing or knocking down the expression of FOXM1 in Caski or Caski/Taxol cells." (PMID 35141332, 2022). "circARHGAP12 exerted the oncogenic role in cervical cancer progression through the m6A-dependent IGF2BP2/FOXM1 pathway." (PMID 36058934, 2022). "In turn, IGF2BP2 modifies circRNA circARHGAP12 and enhances its ability to bind and stabilize the oncogene FOXM1, thus promoting tumor cell proliferation and migration in cervical cancer." (PMID 36072601, 2022).
cervical carcinoma (continued). "Pin1 also contributes to cisplatin resistance through upregulation of the FoxM1 and Wnt/β-catenin signaling pathway in cervical cancer cells." (PMID 33807199, 2021). "m6A-modified circARHGAP12 interacts with IGF2BP2 to enhance FOXM1 mRNA stability, forming circARHGAP12/IGF2BP2/FOXM1 complex, thereby promoting the proliferation and migration of cervical cancer cells." (PMID 34392306, 2021). "In conclusion, we found that circARHGAP12 exerted the oncogenic role in cervical cancer progression through m6A-dependent IGF2BP2/FOXM1 pathway." (PMID 34392306, 2021). "Pin1 has also been reported to enhance EMT and chemoresistance by upregulating FoxM1 and the Wnt/β-catenin signaling pathway in cervical cancer cells." (PMID 33807199, 2021). "One report revealed that miR-342-3p suppresses cell proliferation, migration, and invasion by targeting forkhead box protein M1 (FOXM1) in human cervical cancer." (PMID 32938459, 2020). "For example, circCLK3 acted as a miRNA sponge to decrease expression of miR-320a, which targeted and repressed FoxM1 expression, and thereby promotes a variety of malignant phenotypes of cervical cancer, such as cell proliferation, EMT, migration and invasion." (PMID 33041665, 2020). "Hh and FOXM1 overexpression have been observed in cervical cancer tissue, wherein Shh, PTCH1 and GLI1 correlated with the pathological grade of the tumors and GLI1 and SMO correlated with the clinical stage of the tumors." (PMID 33680951, 2020). "FoxM1, a proliferation‐specific transcription factor, was first discovered in the cervical cancer cell line HeLa." (PMID 32667745, 2020). "Several studies revealed that FOXM1 is overexpressed in various cancer cells, such as ovarian, breast, lung, and cervical cancer cells." (PMID 33053721, 2020). "In order to explore the biological functions of FoxM1 in cervical cancer, a si-RNA target FoxM1 and an overexpression vector of FoxM1 were generated." (PMID 31831728, 2019). "Pearson’s correlation analysis showed that circCLK3 level positively correlated with FoxM1 level in 48 paired cervical cancer tissues." (PMID 31831728, 2019). "In this study, molecular experiments indicated that miR-320a suppressed the expression of FoxM1 through directly binding to 3′UTR of FoxM1 mRNA, thereby inhibiting cell proliferation, migration, and invasion through in cervical cancer." (PMID 31831728, 2019). "qRT-PCR results showed that FoxM1 expression was significantly higher in above 48 paired cervical cancer tissues compared with adjacent normal tissues." (PMID 31831728, 2019). "CircCLK3 promotes cell proliferation, EMT, migration, and invasion through FoxM1, while miR-320a reverses the ability of circCLK3 to promote progression of cervical cancer." (PMID 31831728, 2019). "In conclusion, we have determined the anti-cancer role of miRNA-6852 (miR-SX4) using different cell lines and have shown it to be particularly effective against cervical cancer cells, by significantly regulating transcription factor FoxM1." (PMID 29343703, 2018). "Here, we report new findings of Sufu in regulating the epithelial-to-mesenchymal transition through the FoxM1 transcriptional modulation by 14-3-3ζ protein in cervical carcinoma." (PMID 29371981, 2017). "The newly found miR-216b/FOXM1 link provides a clue to the discovery of the potential mechanism for FOXM1 dysregulation and cervical cancer tumorigenesis." (PMID 28978307, 2017). "FOXM1 has been proved to be a prognostic factor for poor survival in patients with early-stage cervical cancer." (PMID 28978307, 2017). "In this study, we detected the miR-216b level in different cervical cancer cell lines, and found that miR-216b level negatively correlated with the FOXM1 expression." (PMID 28978307, 2017). "It has been found that in cervical cancer cells, miR-216b level had an opposite trend of variation against FOXM1 expression." (PMID 28978307, 2017).
cervical carcinoma (continued). "Modulation of FOXM1 expression through miR-216b regulation shed new lights on the molecular intervention therapy for cervical cancer." (PMID 28978307, 2017). "FOXM1 and miR-216b level were screened in different cervical cancer cell lines, including HeLa, SiHa, Ca Ski, C33A and HCC94." (PMID 28978307, 2017). "In previous study, we focused on a tumor-related transcription factor FOXM1, and explored its role in cervical cancer metastasis." (PMID 28978307, 2017). "To further elucidate miR-216b-FOXM1 regulation relationship, we analyzed FOXM1 and miR-216b level in clinical cervical cancer tissues using western blotting and qRT-PCR analysis." (PMID 28978307, 2017). "Previous experiments have demonstrated that reduction of FOXM1 is a common scenario when AMPK is activated in cervical cancer cells." (PMID 23819460, 2013). "Collectively, these findings confirm that activation of AMPK by hypoxia and glucose deprivation, as well as pharmacological AMPK activators inhibits cervical cancer cell growth, and this effect is dependent on the endogenous expression level of FOXM1." (PMID 23819460, 2013). "Here, we report that activated AMPK (p-AMPK) also inhibits cervical cancer cell growth by counteracting FOXM1 function." (PMID 23819460, 2013). "In this study, we report another molecular mechanism by which AMPK can retard cervical cancer cell growth: inhibition of FOXM1 function via AMPK/AKT/FOXO3a signaling." (PMID 23819460, 2013). "As a result, FOXO3a will be more nuclear-localized and activated to inhibit FOXM1 mRNA expression in cervical cancer cells." (PMID 23819460, 2013). "These evidences imply that the reduction of FOXM1 at both the mRNA and protein levels is due to the presence of FOXO3a in cervical cancer cells." (PMID 23819460, 2013). "Taken together, our results suggest the activated AMPK impedes cervical cancer cell growth through reducing the expression of FOXM1." (PMID 23819460, 2013). "Biochemical and functional studies confirmed that FOXM1 is critically involved in cervical cancer cell growth through upregulating cyclin B1, cyclin D1 and cdc25B and downregulating p27 and p21 expressions." (PMID 23819460, 2013). "In this study, we reported that the activated AMPK inhibits the cell growth by reducing FOXM1 expression in human cervical cancer cells upon treatments with hypoxia, glucose deprivation and pharmaceutical AMPK activators." (PMID 23819460, 2013). "Upon treatment of metformin (25 mM) on the cervical cancer cell line C33A, not only FOXM1 expression diminished remarkably but also the phosphorylation of AKT and the AKT-specific phosphorylation of FOXO3a (Ser253)." (PMID 23819460, 2013). "In fact, we demonstrated that reduction of FOXM1 occurred at both the mRNA but and protein levels in cervical cancer cells." (PMID 23819460, 2013). "We previously reported that there is a progressive increase in FOXM1 level in the progression of human cervical cancer." (PMID 23819460, 2013). "To verify the key role of FOXM1 in cervical cancer, we knocked down FOXM1 in CC cell lines." (PMID 40589640, 2025). "Moreover, FOXO3, which is considered to be a regulator for FOXM1, has been shown to participate in the development of cervical cancer and the lactate-rich microenvironment during HPV infection in cervical squamous carcinoma cell." (PMID 36900213, 2023). "Moreover, miR‐374b targets FOXM1, and its overexpression mediates adverse effects in cervical cancer." (PMID 34890108, 2022). "In conclusion, FOXM1 may promote drug resistance in cervical cancer cells by regulating ABCC5 gene transcription." (PMID 35141332, 2022). "We rationalized that a cervical cancer cell HeLa with a different origin than MSC could validate the YAP/FOXM1 axis’s functional role based on our previous studies showing the molecular similarity across the organ-based cancer classifications." (PMID 35356283, 2022). "FOXM1 promotes drug resistance in cervical cancer cells by regulating ABCC5 gene transcription." (PMID 35141332, 2022).
cervical carcinoma (continued). "It has been reported that miR-216b inhibited cell proliferation by FOXM1 in cervical cancer." (PMID 35756697, 2022). "Evidences had revealed the critical role of FOXM1 in cervical cancer." (PMID 34392306, 2021). "Thus, our data suggest that circARHGAP12/m6A/IGF2BP2/FOXM1 axis in the cervical cancer tumorigenesis." (PMID 34392306, 2021). "Pearson’s correlation analysis indicated that the expression level of miR-320a negatively correlated with FoxM1 expression in these 48 paired cervical cancer tissues (R = −0.5084, p = 0.01), which implies that miR-320a may negatively regulate FoxM1 expression." (PMID 31831728, 2019). "Our findings suggest that the circCLK3/miR-320a/FoxM1 axis plays a key role in the progression of cervical cancer, and may well be a biomarker for diagnosis and target for therapy." (PMID 31831728, 2019). "The FoxM1 downregulation by the siRNA induced necrosis by approximately 1.8-fold in HeLa; 1.6-fold in CaSki and 1.9-fold in SiHa, while miR-SX4 transfection induced it by 4~16 fold, suggesting that miR-SX4 has more potent anti-cervical cancer property than si-FoxM1 alone." (PMID 29343703, 2018). "Hence FoxM1 is also involved with the cell survival and silencing its expression leads to increased necrosis in cervical cancer cell line." (PMID 29343703, 2018). "In cervical cancer, E6 oncoprotein augmented the expression of FoxM1 through MZF1/NKX2." (PMID 29554906, 2018). "Although there is report that miR-342-3p could suppress the proliferation and metastasis in cervical cancer by targeting FOXM1, the FOXM1- microRNAs modulation pathways in cervical cancer cells remains to be discovered." (PMID 28978307, 2017). "Functional assay demonstrated that miR-216b could inhibit the proliferation of cervical cancer cells by down-regulating p-Rb, c-myc and cyclinD1, which were downstream targets or important regulators of FOXM1." (PMID 28978307, 2017). "To clarify miRNAs-FOXM1 modulation pathways, in this study, we investigated the relationships between miR-216b and FOXM1 and the role of miR-216b in cell proliferation and prognosis of cervical cancer patients." (PMID 28978307, 2017). "Repressing of miR-216b stimulated cervical cancer cell proliferation, whereas silencing FOXM1 expression could reverse this effect." (PMID 28978307, 2017). "Since miR-216b targets and suppresses FOXM1, it may also be related to the prognosis of cervical cancer patients." (PMID 28978307, 2017). "FOXM1 was a well-accepted oncogene that is targeted by miR-342-3p in cervical cancer." (PMID 27716361, 2016). "Upon treatment of AICAR (1 mM), A23187 (2 μM), metformin (25 mM), glucose deprivation and hypoxia on the cervical cancer cell lines Caski, C33A and HeLa, we found that FOXM1 expression was drastically decreased while AMPK activity [p-AMPK (Thr172)]was elevated concomitantly." (PMID 23819460, 2013). "We then examined whether the PI3K/AKT inhibitor LY294002 could reduce FOXM1 expression in cervical cancer cells." (PMID 23819460, 2013). "However, mounting evidence supports a link between aberrant expression of FOXM1 and human carcinomas such as pancreatic cancer, basal cell carcinomas, glioblastomas and cervical cancer." (PMID 21858223, 2011). "Our study not only provides single-cell and experimental evidence for the treatment of cervical cancer with FOXM1, but also suggests that there may be a potential connection between FOXM1 and TOP2A, but this hypothesis still needs to be verified experimentally." (PMID 40589640, 2025). "Moreover, the C20 FOXM1 antibody could immunoprecipitate EPS8 in another cervical cancer cell line C33A." (PMID 30941306, 2019). "In this study, we found that circCLK3 and FoxM1 both possess binding sites of miR-320a, and demonstrated that circCLK3 promotes the expression of FoxM1 by sponging miR-320a, forming a new theoretical basis for cervical cancer progression and creating a possible direction for targeted therapy." (PMID 31831728, 2019).
cervical carcinoma (continued). "Hence using these two approaches, we find it impossible to perform the rescue experiment correctly to confirm that FoxM1 could restore G2/M cell arrest or necrosis in cervical cancer cells." (PMID 29343703, 2018). "Therefore, FOXM1 could act as a prognostic marker of cervical cancer, and a promising tumor-specific marker which has potential application value in molecular intervention therapy." (PMID 28978307, 2017). "Therefore, we proved that FOXM1 was a direct and functional target of miR-216b, and like FOXM1, miR-216b may act as a prognostic marker of cervical cancer patients." (PMID 28978307, 2017). "Given that activation of AMPK leads to growth inhibition of cervical cancer cells through reduction of both the mRNA and protein levels of FOXM1, we sought to determine whether enforced expression of exogenous FOXM1 could counteract the AMPK-induced suppressive effect." (PMID 23819460, 2013). "For example, in cervical cancer, IGF2BP2 recognizes m6A modifications in circARHGAP12, which in turn promotes the stabilization of forkhead box M1 (FOXM1) mRNA." (PMID 39596216, 2024). "The candidate genes SPP1, FOXM1, LYN, COL6A3, CCL21, TTK and MELK at mRNA level, emerge as promising candidate markers for cervical cancer prognosis and also emerge as potential therapeutic drug targets." (PMID 33829064, 2021). "In summary, circCLK3 acts as a miR-320a sponge to relieve its suppression on FoxM1 expression, and thereby promotes cell proliferation, EMT, migration, and invasion of cervical cancer." (PMID 31831728, 2019). "CircCLK3 acts as a ceRNA of miR-320a to abolish its suppressive effects on target gene FoxM1, and thereby promotes cell proliferation, EMT, migration and invasion of cervical cancer." (PMID 31831728, 2019). "Taken together, FoxM1 promotes cell proliferation, EMT, migration, and invasion of cervical cancer cells." (PMID 31831728, 2019). "Downregulation of EPS8 using shRNAs suppressed expression of FOXM1 and the FOXM1-target CCNB1, and slowed down G2/M transition in cervical cancer cells." (PMID 30941306, 2019). "Taken together, miR-320a reversed the ability of circCLK3 to promote the expression of FoxM1, cell proliferation, EMT, migration, and invasion in cervical cancer." (PMID 31831728, 2019). "It was confirmed that as a contrast to FOXM1, high expression of miR-216b was related to earlier FIGO stage, better histological type and better survival status in cervical cancer patients." (PMID 28978307, 2017). "Taken together, our data support that inhibition of FOXM1 by AMPK activation is attributed to the repression on AKT and its downstream, AKT-specific phosphorylation of FOXO3a (Ser253) in cervical cancer cells." (PMID 23819460, 2013). "Interestingly, activated AMPK could not cause any significant changes in FOXM1 in cervical cancer cells in which endogenous FOXO3a levels were knocked down using siRNAs, suggesting that FOXO3a is involved in the suppression of FOXM1." (PMID 23819460, 2013). "For example, the addition of anti forkhead box M1 (FOXM1) and heat shock factor (HSF1) aptamers to breast and cervical cancer cell lines showed the inhibition of their downstream transcriptional programs and led to impaired cell growth and apoptosis, respectively." (PMID 36358889, 2022). "The present study assessed whether resistance to paclitaxel was increased following upregulation of FOXM1 and ABCC5 in cervical cancer cells." (PMID 35141332, 2022). "In our study, the relative T/ANT (cancer tissues/adjacent non-cancer tissues) ratio of FOXM1 and miR-216b expression was examined in cervical cancer tissues, whereas in TCGA studies, cancer tissues/normal controls were compared." (PMID 28978307, 2017). "Further analysis confirmed that miR-216b inhibits cell proliferation by repressing endogenous FOXM1 in cervical cancer cells and tissues, and negative correlation existed between miR-216b and FOXM1 with coefficient r − 0.805." (PMID 28978307, 2017).